NLRP3 (NLR family pyrin domain containing 3)
Diseases named in the same sentence as NLRP3 in open-access papers (continued):
Sharing a sentence is not in itself a finding about the gene and the disease.
diabetic nephropathy (continued). "NLRP3 inflammasome was activated by the inhibition of podocyte autophagy in high-fat diet-induced diabetic nephropathy mice, and silencing of NLRP3 effectively restored autophagy in podocytes, suggesting that NLRP3 is a negative regulator of autophagy." (PMID 40362581, 2025). "Research has shown that inhibiting the NLRP3 inflammasome in diabetic nephropathy improves podocyte injury by suppressing lipid accumulation." (PMID 41357229, 2025). "In db/db and STZ-treated diabetic nephropathy mice, miR-10a/b curbs NLRP3 inflammasome activation, reducing pro-inflammatory cytokines IL-1β and IL-This notably improves renal inflammation and alleviates albuminuria." (PMID 40841164, 2025). "WTAP integrates inflammatory-oncogenic processes, driving NLRP3 activation in diabetic nephropathy, enabling epigenetic remodeling through TEX41 degradation in RCC, and defining molecular subtypes in lupus nephritis." (PMID 40895041, 2025). "Alterations in SERPINB5 expression have been observed in UC epithelial cells, while TRIM29 has been demonstrated in promoting pyroptosis of diabetic nephropathy podiocytes through the NF-kB/NLRP3 inflammasome pathway." (PMID 38426148, 2024). "There is little research on thechanges of NLRP3 inflammasome and related cellsand molecules in early diabetes kidney disease(EDKD) in the elderly." (PMID 39876912, 2024). "Extracted keywords predominantly focus on NLRP3 inflammatory, diabetic kidney disease, mitochondria, iron overload, and cardiomyopathy." (PMID 38510357, 2024). "Recent research indicates that the activation of the NLRP3 inflammasome is crucial in the development of diabetic kidney disease (DKD)." (PMID 39723074, 2024). "Over the past five years, key topics in this field have revolved around the “heart”, “damage”, “caspase 1 activation”, “NLRP3”, and “diabetic kidney disease”." (PMID 39717099, 2024). "It’s notable that” NLRP3 “and “diabetic kidney disease” have persisted in breaking out up until 2023." (PMID 39717099, 2024). "Wu used the NLRP3-specific inhibitor MCC950 and NLRP3 KO mice to demonstrate that NLRP3 stimulates fatty acid synthesis in diabetic nephropathy through increased expression of the fatty acid synthesis genes SREBP1 and SREBP2." (PMID 38464721, 2024). "The NLRP3 inflammasome and pyroptosis cascade have been investigated in various kidney diseases, including chronic kidney disease, diabetic nephropathy and lupus nephritis." (PMID 39114498, 2024). "The activation of NLRP-3 inflammasome was detected in endothelial cells and podocytes of diabetic humans, which aggravated diabetic nephropathy." (PMID 39769227, 2024). "Another study showedthat in diabetic nephropathy, optic nerve proteinsinhibit the activation of NLRP3 inflammatory vesiclesby enhancing autophagy in renal tubular cells." (PMID 39876912, 2024). "Collectively, these studies underscore the ability of traditional Chinese medicine to regulate NLRP3 vesicle activation and improve diabetic nephropathy outcomes through multiple pathways." (PMID 39104818, 2024). "For example, both IL-1β and TNF-α are released in high concentrations in IRI, and IL-1β is known to promote renal steatosis in models of diabetic nephropathy through upregulation of SREBP1 in an NLRP3-dependent fashion." (PMID 38464721, 2024). "The paper aims to investigate the expression level of NLRP3 inflammasome and its related cell molecules in early diabetes kidney disease (EDKD) in the elderly and its clinical application value." (PMID 39876912, 2024). "Systemic NLRP3 inflammasome activation appears pivotal in the development and progression of diabetic nephropathy." (PMID 38740765, 2024). "It is known that pro-inflammatory cytokines produced by a multiprotein complex NLRP3 inflammasome are drivers of diabetic kidney disease." (PMID 38254639, 2023).
diabetic nephropathy (continued). "Podocyte-specific depletion of NLRP3 demonstrated a positive role for the NLRP3 inflammasome in protecting podocytes from glomerular pathology in a mouse model of diabetic kidney disease." (PMID 37564649, 2023). "S-adenosylhomocysteine inhibition enhanced TXNIP-mediated oxidative stress and NLRP3 inflammasome activation, which aggravated podocyte injury and diabetic nephropathy." (PMID 37814350, 2023). "The activation of the NLRP3 inflammasome and subsequent production of pro-inflammatory cytokines have been identified as critical drivers of diabetic kidney disease." (PMID 37371054, 2023). "In conclusion, in the present study, we revealed that coptisine remitted diabetic nephropathy via suppressing the activation of NLRP3 inflammasome." (PMID 37197172, 2023). "Increasing evidence reveals the vital role of NLRP3 inflammasome in the pathogenesis of diabetic nephropathy." (PMID 37197172, 2023). "For example, podocytes, epithelial cells critical for the maintenance of kidney filtration, have been reported to express NLRP3 and to release IL-β in diabetic kidney disease, contributing to filtration barrier dysfunction and kidney injury." (PMID 37744356, 2023). "For instance, some scholars clarified that the Huangkui capsule mitigated renal tubular EMT in diabetic nephropathy in rats through the repression of the NLRP3 inflammasome and TLR4/NF-κB pathway." (PMID 36793762, 2023). "Many researchers have reported the important role of NLRP3 inflammasome in diabetic kidney disease, hypertensive renal disease, ischemic renal disease, and UUO." (PMID 37685978, 2023). "In a later study, the same authors showed that selective depletion or overexpression of the NLRP3 inflammasome in podocytes, the epithelial cells of the glomerular filtration barrier, led to protection or aggravation of diabetic kidney disease, respectively." (PMID 37744356, 2023). "The excessive TXNIP signal promotes oxidative stress and follows NLRP3 inflammasome motivation, contributing to diabetic nephropathy progression." (PMID 37229425, 2023). "In diabetic nephropathy, NETs promote NLR family pyrin domain-containing 3 (NLRP3) inflammasome activation and glomerular endothelial dysfunction." (PMID 36430491, 2022). "In the study of diabetic nephropathy, knockdown of NLRP3 decreased the expression of thioredoxin-interacting protein and NOX4 and the production of superoxide in the diabetic kidney, and improved renal function." (PMID 35711428, 2022). "Huangkui capsule attenuated tubular epithelial-mesenchymal transition in diabetic nephropathy mice by inhibiting TLR4/NF-κB/NLRP3 pathway." (PMID 36387904, 2022). "This review will evaluate a role for the priming and activation of the NLRP3 inflammasome in the context of the pathogenesis and progression of diabetic nephropathy." (PMID 35755447, 2022). "Several studies describe the role of NLRP3 in driving tubulointerstitial injury in diabetic kidney disease." (PMID 35755447, 2022). "Under diabetic sittings, a recent study found that inhibition of SAHH activity aggravated the process of diabetic nephropathy partly by inducing NLRP3 inflammasome activation and oxidative stress." (PMID 35964109, 2022). "The NOD-like receptor family pyrin domain containing 3 (NLRP3) is a potential target of diabetic nephropathy." (PMID 36615475, 2022). "Reduced gene expression of NLRP3 and caspase-1 (signal 1) by minocycline has also been described in mouse models of diabetic nephropathy or Huntington disease." (PMID 35130879, 2022). "Several studies have since illustrated the widespread impact of NLRP3 inflammasome activation in diabetic nephropathy through its role in glomerular injury." (PMID 35755447, 2022). "In turn, inhibition of NLRP3 inflammasome activation ameliorates renal injury and fibrosis in diabetic nephropathy (DN), suggesting that targeting the NLRP3 inflammasome is a promising approach for the treatment of DN." (PMID 36189207, 2022).
diabetic nephropathy (continued). "In summary, these findings support the concept that NLRP3 inflammasome activation is instrumental in mediating renal tubule damage in diabetic nephropathy." (PMID 35755447, 2022). "Pyroptosis mediated by the NLRP3 inflammasome plays an important role in the development of diabetic nephropathy." (PMID 36387904, 2022). "LincRNA-Gm4419 accelerates inflammation and fibrosis by NF-kB/NLRP3 inflammasome-mediated mechanisms in diabetic nephropathy." (PMID 35366793, 2022). "Studies have shown that in patients with diabetic nephropathy, hyperglycemia can activate NLRP3, which coexists with ASC and pro-caspase-1 to form the NLRP3 inflammasome, and then activates caspase-1." (PMID 36552271, 2022). "In summary and irrespective of the pathway which is activated, increased activation of the NLRP3 inflammasome leads to the regulation and execution of inflammatory responses, a process that becomes dysregulated in diseases including diabetic nephropathy." (PMID 35755447, 2022). "5‐BDBD can also inhibit ATP‐P2X4R‐mediated NLRP3 inflammasome activation in tubulointerstitial inflammation in diabetic nephropathy." (PMID 36353932, 2022). "In an in vitro model of diabetic nephropathy, either miR-34c inhibition or NLRP3 overexpression by sh-NEAT1 transfection reverses the exacerbation of pyrophosphorylation and inflammation." (PMID 34712322, 2021). "Contemporary scientific documentation proposes that a few antidiabetic drug groups obstruct the NLRP3 inflammasome signaling pathway and evince anti-inflammatory actions in diabetic nephropathy patients as well as experimental animal models." (PMID 34443594, 2021). "NLRP3-mediated inflammation is closely related to the pathological progression of diabetic nephropathy (DN)." (PMID 33995126, 2021). "It has been reported that TXNIP is an important mediator for NLRP3 inflammasome activation, emerged as a target in multiple diseases, including cervical inflammation, diabetic nephropathy, and tubular injury." (PMID 32892306, 2021). "Kcnq1ot1 knockdown and miR-506-3p overexpression reduce pyroptosis by downregulating NLRP3 expression in diabetic nephropathy." (PMID 34858199, 2021). "Among all the LncRNAs, LncRNA MALAT1 involves in regulating inflammation and NLRP3-mediated pyroptotic cell death in multiple diseases, including diabetic atherosclerosis, and diabetic nephropathy." (PMID 34503385, 2021). "miR-34c mediates the effect of NEAT1 on diabetic nephropathy pyrophosphorylation by regulating NLRP3 expression as well as caspase-1 and interleukin-1β expression." (PMID 34712322, 2021). "The Syk/JNK/NLRP3 signaling pathway was involved in diabetic cardiomyopathy and diabetic nephropathy in our previous study." (PMID 34603335, 2021). "NLRP3 knockdown sufficiently ameliorated podocyte autophagy and protected podocytes from diabetic nephropathy-induced injury." (PMID 34512861, 2021). "One study has shown that NLRP3 knockout in diabetic mice protects against diabetic nephropathy, improves the urine albumin/creatinine ratio, and attenuates glomerular hypertrophy, mesangial expansion, interstitial fibrosis, inflammation, and TGF-β1 expression." (PMID 34220546, 2021). "Saxagliptin intervention alleviated diabetic nephropathy by targeting NLRP3 in the rodent model, and notably, gardenoside suppressed NLRP3 through autophagy in the microglial model." (PMID 34566670, 2021). "Another combination therapy with dapagliflozin and saxagliptin ameliorated diabetic cardiomyopathy and diabetic nephropathy in mice by inhibiting proinflammatory cytokines and NLRP3/ASC inflammasome production." (PMID 34124273, 2021). "Small-molecule inhibitors that target NLRP3 and other components of the inflammasome are potential options for the treatment of kidney-related diseases such as diabetic nephropathy." (PMID 32410864, 2020). "In tissue from human renal biopsies, increased expression of NLRP3 mRNA was detected in diabetic kidney diseases." (PMID 32316547, 2020).
diabetic nephropathy (continued). "Here, inhibition of BTK with ibrutinib reduced both NF‐κB and NLRP3 inflammasome activation in the kidney, reduced classical histological markers of early diabetic nephropathy, and protected mice from the development of proteinuria." (PMID 32608058, 2020). "RIPK3 activity and NLRP3 expression were upregulated and fibrotic responses were increased in the kidney cortex of WT mice with established diabetic nephropathy compared to control mice." (PMID 32591618, 2020). "Dihydroquercetin treatment can decrease ROS production and NLRP3 inflammasome activation to improve fibrosis in rats with high fat diet (HFD)/streptozotocin-induced diabetic nephropathy (DN)." (PMID 33390969, 2020). "Inhibition of TXNIP abrogated diabetic nephropathy through inhibition of NLRP3 inflammasome activation in murine streptozotocin (STZ)-induced diabetes." (PMID 31694192, 2019). "NLRP3 or caspase-1 gene knockout and caspase-1 inhibition blocked or even reversed the progression diabetic nephropathy in mice." (PMID 31737627, 2019). "In diabetic nephropathy (DN), NLRP3 inflammasomes promoted disease onset and progress under high-glucose conditions; meanwhile, IL-1β and IL-18 secreted from both immune cells and glomerular resident cells exaggerated disease severity." (PMID 31427885, 2019). "Overall, NLRP3 plays a pivotal role in diabetic kidney disease progression in both inflammasome-dependent and inflammasome-independent ways, depending on the type of renal cells." (PMID 31694192, 2019). "Many studies have reported on the important role of the NLRP3 inflammasome in diabetic nephropathy, hypertensive kidney disease, rhabdomyolysis, UUO and ischemic renal disease." (PMID 30483252, 2018). "NOD-like receptor protein 3 (NLRP3) inflammasome has been implicated in the pathogenesis of numerous renal conditions, including AKI, diabetic nephropathy, and chronic kidney disease." (PMID 30114208, 2018). "The antibiotic minocycline is an Nrf2 activator that reduces renal NLRP3 inflammasome activation in pre-clinical models of diabetic nephropathy in a ROS-dependent manner." (PMID 29515457, 2018). "The NLRP3 inflammasome plays an important role in the pathogenesis of inflammation in diabetic nephropathy (DN)." (PMID 28708885, 2017). "Soluble CD36 is a biomarker of T2D and diabetic nephropathy and coordinates activation of the NLRP3 inflammasome, leading to proinflammatory cytokine release and reduced insulin secretion." (PMID 27864352, 2017). "Taken together, these results reveal that high glucose activates the NLRP3 inflammasome and mediates inflammation in diabetic nephropathy." (PMID 26881256, 2016). "Hyperglycemia along with uric acid and fatty acid activates the NLRP3 inflammasome, which is involved in the occurrence and development of inflammation in diabetic nephropathy." (PMID 26881256, 2016). "Inflammasome was also implicated in inflammatory, autoimmune, and obstructive kidney disease and in ischemia-reperfusion type kidney injury, mostly in rat or mouse models, but the role of NLRP3 inflammasome in diabetic nephropathy remains to be elucidated." (PMID 26273672, 2015). "Furthermore, research has demonstrated that TMD1 can alleviate diabetic nephropathy in mice by inhibiting NF‐κB/NLRP3 inflammasome‐mediated inflammation and apoptosis." (PMID 41503166, 2026). "Moreover, HUA‐induced NLRP3 activation in macrophages is used as the contributors to the progression of diabetic nephropathy." (PMID 41278550, 2025). "Furthermore, it can impede the NLRP3 inflammasome pathway, thus alleviating pyroptosis and diabetic nephropathy podocyte injury." (PMID 40841164, 2025). "We also explored if DIO could ameliorate diabetic nephropathy (DN) in rats by suppressing the NLRP3 inflammasome in the kidneys." (PMID 40458807, 2025).
diabetic nephropathy (continued). "Additionally, pharmacological inhibition of MyD88 by LM8 suppressed inflammation in TECs and prevented diabetic kidney disease in experimental mice probably through the NF-κB/NLRP3 pyroptosis pathway." (PMID 39000237, 2024). "MiRNA-146a and miRNA-223 are key epigenetic regulators of toll-like receptor 4 (TLR4)/tumor necrosis factor-receptor-associated factor 6 (TRAF6)/NOD-like receptor family pyrin domain-containing 3 (NLRP3) inflammasome pathway, which is involved in diabetic nephropathy (DN) pathogenesis." (PMID 39033184, 2024). "Similarly, Ginsenoside Rg5 has been shown to diminish inflammatory responses by inhibiting the activation of the NLRP3 inflammasome, consequently reducing blood glucose, creatinine, and urea nitrogen levels in mice with diabetic nephropathy (DN)." (PMID 39104818, 2024). "Furthermore, apocynin treatment downregulated NLRP3 expression and improved renal function in a rat model of diabetic nephropathy." (PMID 36671008, 2023). "This provides additional evidence for our hypothesis that repressing NLRP3 inflammasome may participate in the function of coptisine on diabetic nephropathy." (PMID 37197172, 2023). "NLRP3 inflammasome relates to the onset of diabetic nephropathy." (PMID 37197172, 2023). "In the present study, we found that coptisine repressed the activation of NLRP3 inflammasome, which may contribute to the effect of coptisine on diabetic nephropathy." (PMID 37197172, 2023). "Tang and co-workers showed that this axis might induce inflammatory response in diabetic nephropathy by promoting NLRP3 inflammasome overactivation." (PMID 37957672, 2023). "The NLRP3 inflammasome exhibits a critical role in diabetic nephropathy pathogenesis." (PMID 37197172, 2023). "NLRP3 inflammasome suppressing may be a promising therapy for the treatment of diabetic nephropathy." (PMID 37197172, 2023). "In conclusion, dysregulated metabolism and inflammation contribute to the development and progression of diabetic kidney disease through various pathways and genes, including dysregulated glucose and lipid metabolism, activation of the NLRP3 inflammasome, and dysregulated JAK/STAT signaling." (PMID 37371054, 2023). "Therefore, as an important antioxidative transcription factor, Nrf2 is a potential activator of NLRP3 inflammasome in various pathological conditions, such as depressive-like behaviors, cerebral ischemia-reperfusion injury, and diabetic nephropathy." (PMID 37596540, 2023). "Overexpression of NLRP3 leading to elevated proinflammatory cytokines IL-1β and IL-18, followed by inflammatory cell infiltration in the glomerulus, was discovered in a study of diabetic nephropathy rats regarding hyperuricemia and dyslipidemia." (PMID 35719709, 2022). "The therapeutic effects of FA on diabetic nephropathy might be related to the regulation of the NLRP3 inflammasome signaling pathway." (PMID 36615475, 2022). "The extent of renal damage in diabetic mice was identical to wild-type mice when bone marrow from Nlrp3-/- and Caspase-1-/- mice was transplanted in db/db mice, and induction of the NLRP3 inflammasome originating from intrinsic renal cells worsened diabetic nephropathy (DN)." (PMID 35204131, 2022). "This review will explore a role for NLRP3 inflammasome activation and signalling in mediating inflammation in diabetic nephropathy, specifically in the glomerulus and proximal tubule, before briefly describing the current position of therapeutic research in this field." (PMID 35755447, 2022). "Mitochondrial ROS promote tubular damage in diabetic nephropathy via the TXNIP/NLRP3/IL-1β axis." (PMID 36189207, 2022). "Consequently, further research is needed to identify clinically safe and effective therapeutics for NLRP3 driven chronic inflammatory diseases, including diabetic nephropathy." (PMID 35755447, 2022). "Previous research has reported the mitochondrial ROS-Txnip-Nlrp3 pathway in diabetic nephropathy." (PMID 35847595, 2022).